INS (insulin)
Diseases named in the same sentence as INS in open-access papers (continued):
Sharing a sentence is not in itself a finding about the gene and the disease.
diabetes (continued). "Insulin is a major peripheral hormone released after food intake and the reduced ability of insulin to act on its target tissue, i.e. insulin resistance (IR), is a hallmark of type 2 diabetes mellitus (T2D) and obesity." (PMID 28487570, 2017). "Studies on the effects of insulin therapy on the cognitive functions of dementia patients are controversial, some of these suggest that insulin increases the risk of dementia in diabetes patients, on the other hand further studies indicate that insulin slow down the cognitive decline in AD patients." (PMID 28890694, 2017). "This study demonstrates that diabetes caused by insulin deficiency can induce abnormality in the proliferation of gingival fibroblasts, which is related to the resistance of Akt phosphorylation induced by insulin." (PMID 29267310, 2017). "Treatments which elevate circulating insulin levels in people with diabetes may increase cancer risk, and insulin analog glargine has been associated with higher risk of breast cancer than human insulin." (PMID 27832382, 2017). "Diabetes mellitus type 1 is an autoimmune disorder characterized by insulin deficiency that can lead to diabetic ketoacidosis crises, poor healing and limb amputations, renal failure, blindness, and heart disease, with a lifelong requirement for insulin." (PMID 28191766, 2017). "Nevertheless, the nature of the role of HNF1A in LADA is unclear, although any gene compromising insulin secretory function could predispose to diabetes." (PMID 28438156, 2017). "Insulin use has been linked to higher likelihood of experiencing hypoglycemia; however, within the group of insulin-treated diabetes, the predictors of hypoglycemia remain unclear." (PMID 28913365, 2017). "However, statin use seems to modestly increase the risk of new-onset type 2 diabetes in individuals with a pre-existing elevated risk for diabetes, probably because they increase insulin resistance and decrease insulin secretion." (PMID 28061854, 2017). "Hyperinsulinemia as a cancer promoting metabolic factor in T2DM patients suggests a CRC risk modifying role for anti-diabetes drugs as insulin analogues and secretagogues elevate serum insulin serum levels in contrast to insulin sensitizers that lower insulin levels." (PMID 28436468, 2017). "SWS plays an important role in glucose regulation and the suppression of SWS may result in decreased insulin sensitivity, leading to impaired glucose tolerance and increased diabetes risk." (PMID 28335761, 2017). "In Europeans with T2DM, DRD was associated with the duration of diabetes and this association could be largely explained by the presence of diabetes-related microvascular complications and insulin treatment." (PMID 29089913, 2017). "Furthermore, we showed that the modified WB is applicable to other diabetes-associated peptide hormones: insulin analogs, glucagon, GLP-1s, somatostatins, ghrelins, and pancreatic polypeptide." (PMID 28761041, 2017). "The association remained significant when fasting insulin, eGFR, smoking, diabetes, ACE inhibitors, sartans or diuretics treatments, use of metformin and pioglitazone were added to the model, but its independence was not retained after inclusion of fibrinogen and ESR values into the model." (PMID 28415730, 2017). "In patients with diabetes, treatment with thiazolidinediones and metformin has also been shown to reduce the risk of developing psoriasis, while regular insulin use may increase psoriasis risk." (PMID 29065479, 2017). "Furthermore, diseases associated with altered insulin production and action such as diabetes and obesity exhibit impaired angiogenic processes that are related to microvascular alterations and the pathogenesis of those diseases." (PMID 28424632, 2017).
diabetes (continued). "The frequencies of all and severe hypoglycemia had a significant positive association with the duration of diabetes (p = 0.000 for both), daily insulin dose (p = 0.000 for both), number of daily insulin injections (p = 0.000 for both), and glycemic variability (p = 0.000 for both)." (PMID 28913365, 2017). "The mechanisms underlying diabetes-associated hyperlactatemia include serious changes in the intracellular glucose metabolism in insulin-sensitive tissues, for example, diminished glycogen synthesis, compromised glucose oxidative metabolism, and increased whole-body rate of nonoxidative glycolysis." (PMID 28077918, 2016). "Lastly, conditions associated with diabetes other than glucose (such as insulin and insulin resistance) may impact CAC cytokine secretion therefore future studies should evaluate other diabetes‐related environments." (PMID 26847726, 2016). "Taken together, the Lanoh (both males and females) have higher risk for diabetes mellitus which may be associated with insulin resistance (in view of the high insulin and hs-CRP levels)." (PMID 27009064, 2016). "Indeed, additional studies are still needed to explore the precise relationships between loss of beta cell insulin production, glucagon-positive cell mass, hyperglucagonemia, and the onset of hyperglycemia in insulin-deficient diabetes." (PMID 28702245, 2016). "Positive associations could be explained by confounding factors: patients with T2D using insulin are usually older, with a longer history of diabetes, more comorbidities, at higher cardiovascular risk and with greater insulin resistance." (PMID 27391319, 2016). "Dysfunction or loss of insulin-secreting β cells in the pancreas is a hallmark of diabetes." (PMID 27399229, 2016). "Several human diabetes GWAS candidates encode transcription factors whose functions in regulating insulin transcription are currently unknown." (PMID 27053133, 2016). "Our previous studies have demonstrated that diabetes could accelerate the development of the cerebral amyloidosis connected to AD pathology in a mouse model of combined insulin-deficient diabetes and AD via STZ injection." (PMID 27406855, 2016). "Diabetes mellitus is a chronic disorder characterized by hyperglycaemia, elicited due to a disfunctional carbohydrate, lipid and protein metabolism with absolute/relative deficiencies in the insulin secretion or its action." (PMID 27003006, 2016). "Vitamin D deficiency (i.e., hypovitaminosis D) is associated with increased insulin resistance, impaired insulin secretion, and poorly controlled glucose homeostasis, and thus is correlated with the risk of metabolic diseases, including type 2 diabetes mellitus (T2DM)." (PMID 26959059, 2016). "The biological mechanisms behind a potential increased risk of breast cancer in women with diabetes are unknown, although are probably related to alterations in circulating concentrations of insulin, insulin-like growth factors and endogenous sex hormones." (PMID 25916213, 2016). "Indeed, ageing can affect both insulin secretion and insulin action, and predisposes to glucose intolerance and diabetes." (PMID 26474776, 2016). "Also, greater GlycA levels, but not hsCRP (data not shown), were associated with more fasting insulin, more pancreatic beta-cell insulin secretion, and less skeletal muscle insulin sensitivity; all indicators of greater diabetes risk." (PMID 27067270, 2016). "Diabetes mellitus is one of the most widespread endocrine diseases, referred to a group of metabolic disorders associated with high blood glucose (hyperglycemia) due to impaired insulin secretion or action." (PMID 28197508, 2016). "Scd1, for example, catalyzes the rate-limiting reaction of monounsaturated fatty acid synthesis and is regulated by leptin, a key regulator of obesity-linked diabetes, through insulin independent mechanisms while FASN deregulation is linked to metabolic diseases and insulin-resistance." (PMID 27855634, 2016).
diabetes (continued). "In addition, it was also shown to be associated with diabetes-related metabolic traits (including higher fasting insulin, glucose and triglycerides, and lower HDL cholesterol), although the association disappeared after adjustment for BMI." (PMID 26878843, 2016). "Since impaired insulin secretion and insulin resistance are the main pathophysiological components of type 2 diabetes, these two defects are likely be the potential mechanism underlying the smoking-diabetes linkage." (PMID 27992538, 2016). "Among the antipsychotics, olanzapine and clozapine (both second generation antipsychotics) have been most strongly linked to diabetes mellitus, because they block insulin secretion as antagonists of acetylcholine muscarinic 3 receptors in the β-cells of the pancreas." (PMID 27389787, 2016). "The rate of cognitive decline associated with diabetes is also increased by the presence of the apoE4 allele, reinforcing emerging hypotheses linking neuronal insulin-signaling dysregulation and Alzheimer’s." (PMID 26823968, 2016). "Diabetes causes vascular rarefaction, which decreases blood vessel density in the skeletal muscles, which may contribute to insulin resistance." (PMID 27220353, 2016). "Moreover, due to the higher fat–lean ratio, indicating a greater load–capacity ratio, increases in BMI in Indian populations elevate diabetes risk to a greater extent than they do in European populations, raising the susceptibility to insulin resistance." (PMID 27458578, 2016). "By contrast, natriuretic peptides are deficient in obesity and diabetes, as obese and insulin-resistant individuals display reduced circulating ANP and BNP levels, despite the fact that these metabolic disorders increase the risk of developing cardiovascular disease and heart failure." (PMID 26684450, 2016). "But could it be that a generalized bacterial infection is able to reduce the secretion of insulin by pancreatic cells and consequently have a causal role in diabetes?" (PMID 27631977, 2016). "Type 2 diabetes mellitus (T2DM) is characterized by progressive insulin secretion defects on the basis of insulin resistance and is accompanied by hyperinsulinemia, hyperglycemia, increased inflammatory mediators, advanced glycation end products and amyloid deposition." (PMID 27729856, 2016). "Interestingly, many of the insulin folding mutations that cause PNDM and the mutant INS-gene-induced diabetes of youth (MIDY) generate unpaired cysteines." (PMID 27926939, 2016). "We did not observe any between-group differences based on ethnicity and GDM diagnostic criteria (fasting glucose level of <5.8 mmol/l or ≥5.8 mmol/l) for predictors such as maternal age, BMI, family history of diabetes, need for insulin in pregnancy and the risk of type 2 diabetes." (PMID 27073002, 2016). "Mechanistically, it is highly plausible that one or more pre-existing disorders of insulin sensitivity and/or production result in predisposition to stress hyperglycaemia during critical illness and may lead to subsequent development of diabetes." (PMID 27677709, 2016). "It is clear now that the mitochondrial pyruvate metabolism performed by pyruvate dehydrogenase and pyruvate decarboxylase plays an important role in regulating the insulin release, which may be the potential cause of the high rate morbidity of diabetes." (PMID 27835892, 2016). "This degree of weight loss most reliably led to diabetes remission in a randomised trial of bariatric surgery and several studies have suggested that similar weight loss is necessary to normalize blood glucose and insulin." (PMID 26879684, 2016). "More rarely, INS dominant mutations give rise to diabetes that presents during infancy." (PMID 26239141, 2016). "However, hypoglycemia is the most common complication in people with endogenous insulin deficient diabetes and typically results from therapeutic hyperinsulinemia, compromised symptomatic responses, and impaired physiologic glucose counterregulatory defenses." (PMID 27597762, 2016).
diabetes (continued). "Recent research on patients with diabetes suggested that insulin therapy and diabetes itself may increase the risk of CRC." (PMID 27535548, 2016). "Similarly, it has been suggested that among East Asians with youth-onset diabetes, genetically determined beta-cell dysfunction predisposes to diabetes in the setting of even mild decreases in insulin sensitivity." (PMID 28702252, 2016). "Similarly, a disulfide bond-disrupting C(A7)Y mutation in the Ins2 gene of Akita mouse, a diabetes model, is a toxic-gain-of-function mutation and results in insulin misfolding, induction of UPR, and eventual death of insulin-producing beta cells." (PMID 27926939, 2016). "Thus, IRS1 and IRS2 together with IGFs and IGFRs have been involved in obesity, birth weight, diabetes mellitus, insulin sensitivity and cancer, showing the genetic associations of their polymorphisms." (PMID 27483248, 2016). "Because β-cell ablation was incomplete after STZ, we aimed at determining whether the action of residual circulating insulin might, in combination with glucagon signaling deficiency, protect Gcgr-/- mice from diabetes." (PMID 27092792, 2016). "As diabetes is mainly characterized by weight loss, high blood sugar and insulin resistance, we first confirmed that our rat model was a model of diabetes by examining the weights, blood sugar levels, and insulin sensitivity index (ISI) values of the animals." (PMID 27438148, 2016). "Studies over extended periods of time are needed to clarify whether high POP exposures affect insulin secretory function and increase the risk of diabetes." (PMID 27266903, 2016). "The loss of normal neuronal insulin signaling in diabetes may be one of the main factors beyond hyperglycemia that plays a role in PNS dysfunction and neuropathic symptoms." (PMID 28066166, 2016). "Vascular endothelial dysfunction, which is closely linked to diabetes and impaired insulin sensitivity, may be a contributing factor to impaired microvascular reactivity." (PMID 27095564, 2016). "There are the studies that indicate the treatment for diabetes, for instance, the long-acting insulin analog glargine may be responsible for the association with the risk of cancer." (PMID 27333326, 2016). "Diabetes mellitus is a metabolic disorder characterized by hyperglycemia caused by either abnormal control of insulin secretion in pancreatic cells or the deterioration of the action of insulin in peripheral tissues." (PMID 27974904, 2016). "Therefore, it is not surprising that these variants are linked to NODAT, another form of diabetes, since the mechanisms controlling insulin production and maintenance of stable glucose levels will both be similar in T2D and NODAT." (PMID 26789123, 2016). "Because symptoms of early diabetes were observed after our patient discontinued paliperidone, we believe that paliperidone-induced insulin secretion may be associated with glucose metabolism in type 2 diabetes." (PMID 27478670, 2016). "High levels of angiotensin II have been reported to possibly play a key role in regulating glucose and insulin and may increase the risk of diabetes." (PMID 28066203, 2016). "Altered β-cell metabolism may underlie both the progressive impairment of insulin secretion and reduced β-cell mass in diabetes." (PMID 27882918, 2016). "Similarly, U-CPR depends on the factor insulin secretion, because it is also associated with diabetes duration." (PMID 26849676, 2016). "Indeed, insulin and glucagon pulsatility is typically disturbed in early stages of diabetes but the molecular mechanisms that underlie the dysregulated secretion are unclear." (PMID 27539300, 2016). "In multivariate analysis, a higher serum bicarbonate was significantly associated with male sex, age at diabetes diagnosis, insulin treatment, diuretic therapy and total serum cholesterol, and negatively with being an ex-smoker, loge(serum triglycerides), serum chloride, CHD and CCI." (PMID 27716263, 2016).
diabetes (continued). "The proponents of this hypothesis claim DE is the cause of a host of outcomes ranging from cancer, diabetes (or aggravate diabetes by affecting insulin levels), and multiple sclerosis to chronic stress and suicide." (PMID 27066469, 2016). "This showed that 30 (19%) of the identified genes have been associated with diabetes, islet/β-cell function or mitochondrial function, and thus might be important for insulin secretion and glucose homeostasis." (PMID 27029739, 2016). "Regression analysis for ischemic stroke risk factors proved that age ≥45 years, male gender, hypertension, coronary artery disease (CAD), diabetes duration ≥10 years, insulin use, and hyperlipidemia were significant independent risk factors for ischemic stroke." (PMID 26989695, 2016). "Specifically, studies examining the possible utility of combined insulin and leptin treatment for control of both hyperglycemia and hyperglucagonemia in insulin-deficient diabetes may be of particular value." (PMID 28702245, 2016). "Diabetes mellitus is classified into two major types: type 1 diabetes mellitus (T1DM), which is caused by a loss of the ability to secrete insulin that possesses an anabolic action on bone, and type 2 diabetes mellitus (T2DM), which develops in the presence of underlying insulin resistance." (PMID 27704396, 2016). "According to our findings, it could be speculated that the low concentration of serum Mg in diabetes subjects was mainly caused by the enhanced insulin resistance, which could increase Mg excretion in urine." (PMID 27756380, 2016). "This phenotypic divergence might allow an experimental tool to analyze pathogenic factors involved in central insulin signalling pathways leading to two different outcomes: prediabetes or overt diabetes." (PMID 27013528, 2016). "Diabetes is a disorder of carbohydrate, protein, and fat metabolism and can represent an absolute insulin deficiency, impaired release of insulin by the pancreatic β cells, inadequate or defective insulin receptors, or production of inactive insulin." (PMID 27294153, 2016). "Furthermore, high sucrose diet results in hepatic steatosis, obesity and diabetes in mice, which are commonly associated with increased body weight gain and insulin tolerance." (PMID 27089323, 2016). "In addition, glucose transport, WNT signaling, muscle development, pancreas development genes, and insulin signaling pathway were associated with hypermethylation in subjects with diabetes or prediabetes." (PMID 27555869, 2016). "This higher risk could also reflect the fact that insulin therapy is usually employed in T2DM patients with a longer diabetes duration, when multiple chronic complications and comorbidities are common." (PMID 28044077, 2016). "In particular, it is worth investigating whether aggregating factors such as insulin resistance and secretion as defined here are universally associated with diabetes management after discharge." (PMID 26849676, 2016). "In an in vivo study using mice, it was reported that PPARγ mRNA and protein levels are down-regulated by fasting and insulin-deficient diabetes while a diet rich in fatty acids increases adipose tissue expression of PPARγ in normal mice and induces PPARγ2 expression in the liver of obese mice." (PMID 26797605, 2016). "In summary, LXRs are implicated in the protection against diabetes through modulation of glucose metabolism, β-cell insulin secretion, and inflammatory signaling, including recent developments indicating vasoprotection from hyperglycemia-induced endothelial dysfunction." (PMID 26611207, 2016). "The two-day restriction was also associated with increased urine levels of beta-aminoisobutyric acid and increased TCA metabolites, which have both been linked to improved mitochondrial function and insulin sensitivity and reduced risk of diabetes, obesity and cardiovascular disease." (PMID 27233359, 2016).